SPEM2 (SPEM family member 2)
Synonyms: C17orf74
Tractability: Antibody: UniProt predicts a signal peptide or a membrane-spanning region.
Gene: Protein-coding gene on chromosome 17 (7,425,616 to 7,427,568, forward strand). Ensembl gene ENSG00000184560.
Subcellular location: Membrane
Subcellular location (Human Protein Atlas): Golgi apparatus
Gene Ontology:
Cellular component: membrane
Genetic constraint (gnomAD): Loss-of-function variants: 16 observed, 13.89 expected, observed/expected ratio (o/e) 1.15, 90% interval 0.78 to 1.71. The upper end of that interval is the gene's LOEUF score, 1.71, which puts it in group 6 of 6, group 1 being the genes least tolerant of losing a copy. Missense variants: 678 observed, 715.58 expected, observed/expected ratio (o/e) 0.95, 90% interval 0.89 to 1.01. Synonymous variants: 268 observed, 285.14 expected, observed/expected ratio (o/e) 0.94, 90% interval 0.85 to 1.04.
Homologues: Orthologues: chimpanzee SPEM2 (97% identical), macaque SPEM2 (87% identical), rabbit SPEM2 (69% identical), dog SPEM2 (66% identical), pig SPEM2 (65% identical), mouse Spem2 (62% identical), rat Spem2 (61% identical), guinea pig SPEM2 (58% identical).
Diseases named in the same sentence as SPEM2 in open-access papers:
SPEM2 is named in the same sentence as 3 diseases in open-access papers, as found by Europe PMC text mining. Sharing a sentence is not in itself a finding about the gene and the disease. The quoted sentences say what the papers report.
male infertility (2 papers, 2022 to 2024). The inability of the male to effect fertilization of an ovum after a specified period of unprotected intercourse. "SPEM1 (Spermatid Maturation 1) and SPEM2 (SPEM Family Member 2) genes are related to spermatid maturation and flagelled sperm motility, and both are linked to reproductive disorders such as male infertility, spermatogenic failure and oligospermia." (PMID 35286314, 2022). "Mice deficient for Spem2 develop male infertility associated with spermiogenesis impairment." (PMID 38421455, 2024). "Understanding the molecular role of SPEM2 could provide new insights into future therapeutic treatment of human male infertility and development of non-hormonal male contraceptives." (PMID 38421455, 2024). "As expected, Spem2-null sperm could not fertilize eggs by natural mating: Sperm from Spem2−/− mice yielded no (0%) two-cell embryos, whereas the average fertilization rate using sperm from wt mice was 87.9%, which further confirmed the male infertility phenotype of Spem2−/− mice." (PMID 38421455, 2024).
Infertility (1 paper, 2024). "The findings suggested that the infertility of Spem2−/− males was primarily caused by fertilization failure rather than embryonic developmental disabilities." (PMID 38421455, 2024). "Given that human SPEM2 exhibits testis-enriched expression, and its function may be conserved in humans as well, it is a potential causative gene for human infertility, which makes genetic diagnosis possible in the future." (PMID 38421455, 2024). "To unveil the reason for the infertility of Spem2−/− mice, we paid close attention to the development and phenotypes of KO males." (PMID 38421455, 2024). "The serum testosterone levels were also normal in Spem2−/− mice, suggesting that infertility was not caused by hormonal deficiencies." (PMID 38421455, 2024). "However, the infertility of Spem2−/− males cannot be rescued by in vitro fertilization, suggesting that defective sperm–egg interaction may also be a contributing factor." (PMID 38421455, 2024).
SPEM2 also shares sentences with these, for which no sentence is quoted: oligospermia (1 paper).